VMP1 (vacuole membrane protein 1)
Diseases named in the same sentence as VMP1 in open-access papers (continued):
Sharing a sentence is not in itself a finding about the gene and the disease.
esophageal adenocarcinoma (1 paper, 2024). A malignant tumor with glandular differentiation arising predominantly from Barrett mucosa in the lower third of the esophagus. "Firstly, the RPS6KB1/VMP1 fusion is suggested to result in a dysfunctional protein incapable of inducing autophagy in esophageal adenocarcinoma." (PMID 38612567, 2024). "In esophageal adenocarcinoma, the RPS6KB1/VMP1 fusion has been found in around 10% of cases." (PMID 38612567, 2024).
heart failure (1 paper, 2026). Inability of the heart to pump blood at an adequate rate to meet tissue metabolic requirements. "Notably, VMP1 expression is elevated in human heart failure, suggesting a pathophysiological role." (PMID 42284404, 2026).
Hepatic steatosis (1 paper, 2026). Steatosis is a term used to denote lipid accumulation within hepatocytes. "Restoring VMP1 in Tmem41b KO mice and TMEM41B in Vmp1 KO mice partially corrected defective VLDL secretion and hepatic steatosis in these single KO mice, respectively." (PMID 41638479, 2026).
lymph node metastasis (1 paper, 2021). "By analyzing the expression of ATG genes both in TCGA and GSE62254, the results showed that VMP1 and ATG4A were over-expressed in patients with lymph node metastasis." (PMID 33604190, 2021). "Low expression of VMP1 and ATG4A suggested absence of lymph node metastasis (P = 0.0018, 0.015, correspondingly)." (PMID 33604190, 2021). "VMP1 and ATG4A were low-expressed in patients without lymph node metastasis." (PMID 33604190, 2021).
metastatic tumors (1 paper, 2019). "Because VMP1 is necessary for the initial steps of autophagy and autophagy is high in metastatic tumors, the effect of high VMP1 levels on distant recurrence free survival (DRFS) was analyzed in the two cohorts for which there were data." (PMID 31442252, 2019).
pancreatic diseases (1 paper, 2020). "We previously characterized VMP1 (Vacuole Membrane Protein 1) as an essential autophagy related protein that mediates autophagy in pancreatic diseases." (PMID 32655498, 2020).
Perry syndrome (1 paper, 2023). Perry syndrome is a rare inherited neurodegenerative disorder characterized by rapidly progressive early-onset parkinsonism, central hypoventilation, weight loss, insomnia and depression. "Similar axonal enlargements were found in the WDR45cKO mice, VMP1-deficient DAergic neurons, and Perry syndrome-associated p150Glued-deficient DAergic neurons." (PMID 37292937, 2023).
pulpitis (1 paper, 2025). Inflammation of the dental pulp. "For the phenotype Pulpal and apical diseases, two other loci in chromosomes 2 (near BCL11A) and 9 (near RMI1), and for the phenotype Pulpitis, three other loci in chromosomes 1 (near PDE4B), 9 (near NR4A3), and 17 (near VMP1 and TUBD1) were identified." (PMID 40701953, 2025).
T-cell lymphomas (1 paper, 2020). "This regulatory connection may also play a role in ALCL, since miR21/VMP1 was elevated in ALCL cell lines, is overexpressed in several T-cell lymphomas, and has been shown to support TH17 differentiation." (PMID 32922661, 2020).
tumor (33 papers, 2007 to 2026). "Next, to investigate the molecular mechanisms underlying the tumor‐promoting function of VMP1, we determined the effect of VMP1‐OE on autophagy." (PMID 41589276, 2026). "The vacuole membrane protein 1 (VMP1) gene encodes a transmembrane protein that plays a key regulatory role in the autophagy process and acts as a tumor suppressors." (PMID 35860595, 2022). "We next analyzed associations between VMP1 expression and clinical pathological parameters, including the tumor grade, isocitrate dehydrogenase (IDH) status, 1p/19q codeletion, TERT status, and O6-methylguanine DNA methyltransferase (MGMT) promoter status." (PMID 34311746, 2021). "On the other hand, VMP1 expression is activated in PANC-1 human tumor cells carrying mutated (G12D) KRAS." (PMID 32655498, 2020). "Among the microRNAs regulated by hypoxia, miR-210 is the critical microRNA implicated in tumor initiation and metastatic potential by targeting different downstream molecules including genes expressed under normoxia and vacuole membrane protein 1 (VMP1)." (PMID 23241400, 2012). "The FDA‐approved anti‐VEGFA antibody, bevacizumab (BEV), can counteract VMP1's tumor‐promoting effect in GBM." (PMID 41589276, 2026). "We then used a xenograft model to determine the functional dependency of VMP1 in mediating tumor growth within different TME and found that GBM cells with VMP1 overexpression (VMP1‐OE) would promote subcutaneous tumor growth in mice." (PMID 41589276, 2026). "Here, we report for the first time the pro‐angiogenic function of VMP1 in promoting tumor growth in GBM through VEGF‐A‐mediated endothelial cell activation." (PMID 41589276, 2026). "It is therefore likely that the TME, and in particular the tumor vasculature, represents a context‐dependent factor essential for the functional interpretation of VMP1 in cancer." (PMID 41589276, 2026). "on the tumor‐promoting role of VMP1, which demonstrated growth impairment in VMP1‐depleted GBM cells through blockade of autophagic flux." (PMID 41589276, 2026). "Our findings were further reinforced by using therapeutics that target VEGFA in a VMP1‐driven tumor model." (PMID 41589276, 2026). "Consistently, VMP1 depletion in tumor cells (shVMP1) reduced tumor growth in vivo and prolonged animal survival when compared to control (shNC) (log‐rank p = 0.0002)." (PMID 41589276, 2026). "The tumor‐promoting function of VMP1 was also supported by the significant increase in Ki‐67 proliferation index in VMP1‐overexpressing tumors." (PMID 41589276, 2026). "Treatment with bevacizumab, a monoclonal antibody against VEGFA, significantly inhibited VMP1‐driven tumor growth and prolonged survival in mice." (PMID 41589276, 2026). "Recently, we identified ubiquitination as a post-translational modification of VMP1 from the initial steps of autophagosome biogenesis from in vitro studies with human tumor cells." (PMID 40243995, 2025). "Conversely, in the other study, the authors demonstrate that the inactivation of the von Hippel–Lindau (VHL) tumor suppressor gene results in a HIF-1α/miR 210-dependent decrease in VMP1 expression." (PMID 38612567, 2024). "The post-translational modification of VMP1, specifically its ubiquitination, has emerged as another layer of regulation that impacts autophagy in tumor cells." (PMID 39100095, 2024). "Our results indicate that ubiquitination is a novel post-translational modification of VMP1 during autophagy in human tumor cells." (PMID 37629161, 2023). "Both pathways of VMP1 transcriptional regulation promote tumor cell resistance to anticancer treatments." (PMID 37629161, 2023). "Vacuole membrane protein 1 (VMP1) is an important autophagy-related protein that plays a role in tumor genesis and progression." (PMID 36672345, 2023). "Previously, we found that the expression of the transmembrane protein VMP1 triggers autophagy in human tumor cells." (PMID 37629161, 2023).
tumor (continued). "Frequent loss-of-function mutations were also observed for CD58, IGLL5, IRF1, LTB, MGA and VMP1 in blood cancers, implicating a potential tumour-suppressive role of these genes in the pathogenesis in this tissue type." (PMID 33420369, 2021). "Vacuole membrane protein 1 (VMP1) is a critical autophagy-associated protein with roles in oncogenesis and tumor progression." (PMID 34311746, 2021). "We found that VMP1 promotes tumor growth and progression and mediates resistance to chemotherapy and radiotherapy by manipulating autophagy." (PMID 34311746, 2021). "The vmp1 deletion strain showed the strongest reduction in virulence with tumor formation being entirely abolished in infected plants." (PMID 34093627, 2021). "Due to the important role of VMP1 and miR-21 in the development of tumor, this novel regulatory mechanism will contribute to explore the tough issues in CRC, such as proliferation, invasion, metastasis, and drug resistance." (PMID 33318473, 2020). "For instance, miR-210 and miR-155, which are overexpressed in HCC and CRC, promote the metastatic potential of HCC cells by targeting the vacuole membrane protein 1 (VMP1), in this way being an example of tumor- to- stroma communication." (PMID 28392501, 2017). "As we begin to understand more about the intricate interplay between VMP1, autophagy, and tumor progression, the development of more personalized treatments that specifically target the essential survival mechanisms may bring new promises." (PMID 41589276, 2026). "As such, the role of autophagy in cancer is widely acknowledged to be context‐dependent and may range from being tumor‐promoting to tumor‐suppressing, as is the case for VMP1 across various cancer types." (PMID 41589276, 2026). "In this study, we showed that the use of BEV can abrogate the tumor‐promoting effect of VMP1 in GBM, and that targeting VMP1 or VMP1‐associated pathways may serve as a novel therapeutic approach, either in combination with or as an alternative to BEV." (PMID 41589276, 2026). "Emerging evidence suggests that VMP1 may have context‐dependent functions across diverse cancer types and different tumor microenvironments, both within the context of autophagy and beyond." (PMID 41589276, 2026). "Furthermore, the opposing effects of VMP1 expression on invasion capabilities in cancer cells compared to CAFs add another layer of complexity to its role in the tumor microenvironment." (PMID 38612567, 2024). "However, VMP1’s role in various cancers is context-dependent, influenced by factors such as cellular context, tumor microenvironment, tumor stage, and the specific pathways involved." (PMID 38612567, 2024). "We conclude that ubiquitination is a novel post-translational modification of VMP1 in the context of the VMP1-mediated autophagy of human tumor cells, and it might have clinical relevance in the resistance of cancer cells to therapy." (PMID 37629161, 2023). "It is very interesting to note that both VMP1 and Cdt2 play important roles in tumor resistance." (PMID 37629161, 2023). "We found that the CRL4/Cdt2 E3 ligase is involved in VMP1 ubiquitination as a novel post-translational modification, which might be involved in the regulation of the autophagic pathway in human tumor cells." (PMID 37629161, 2023). "In this study, we used tumor cells as an experimental model to study the ubiquitination of VMP1." (PMID 37629161, 2023). "Here we found fusions with VMP1 as 3′ partner in 64 tumours (5.9% of the samples)." (PMID 35182081, 2022). "At the same time, it was found that vmp1 and miRNA-21 could regulate each other near the downstream region, and vmp1 might play an important role in tumor proliferation, invasion, and metastasis." (PMID 36012210, 2022).
tumor (continued). "This contradiction may be partially explained by different types of tumor, but more importantly, by the role of VMP1 in autophagy." (PMID 34513657, 2021). "Moreover, miR-210 can bind to the 3’UTR of VMP1 and regulate the invasion and migration of tumor cells." (PMID 34631221, 2021). "Since the metastasis of CAFs is similar to that of tumor cells, we hypothesized that the invasion and migration of CAFs in the tumor microenvironment were also regulated by VMP1." (PMID 34631221, 2021). "E2F1 expression induced VMP1 mRNA expression in PANC-1 tumor cells." (PMID 32655498, 2020). "Thus miR-21 would increase itself expression via miR-21/VMP1 feedback loop in the tumor microenvironment of CRC." (PMID 33318473, 2020). "The regulation loop of miR-21/VMP1 can increase miR-21 expression and reduce VMP1 expression, which could reduce the drug sensitivity of tumor cells to 5-FU." (PMID 33318473, 2020). "In order to understand whether VMP1 ́s expression levels could indicate severity of disease the mRNA values were correlated with the tumor ́s clinical and pathological characteristics." (PMID 31442252, 2019). "Next, we asked whether VMP1‐mediated tumor growth was dependent on VEGFA." (PMID 41589276, 2026). "Therefore, VMP1 plays a relevant role in tumor pathophysiology." (PMID 37629161, 2023). "VMP1 ubiquitination may be of clinical relevance in tumor-cell-therapy resistance." (PMID 37629161, 2023). "Therefore, VMP1 is considered to play a vital role in the process of tumor metastasis." (PMID 34631221, 2021). "Thus, VMP1 could support tumor progression at various points, both independent and dependent on HER2." (PMID 31442252, 2019). "Nevertheless, our findings reveal that high VMP1 expression predicts poor survival in GBM and drives pro‐angiogenic tumor growth independently of autophagy via VEGFA‐VEGFR2 signaling." (PMID 41589276, 2026). "Subsequently, TMEM genes expression of stromal cells in normal and tumor tissues was compared, and TMEM158, TMEM38B, VMP1 and TMEM45A were recognized as DEGs." (PMID 37265785, 2023). "The GSE54129 GC dataset and LASSO regression model (tumor vs. normal) were employed, and 6 significant differentially expressed genes (LAMP5, CEBPB, ARMC9, PAOX, VMP1, POC1A) were identified." (PMID 33052878, 2020). "This study reveals a previously unrecognized interaction between VMP1 and the tumor microenvironment (TME) that is independent of its autophagic roles, highlighting both mechanistic and translational significance." (PMID 41589276, 2026). "Additionally, this article discusses VMP1 gene fusions, especially with ribosomal protein S6 kinase B1 (RPS6KB1), shedding light on potential implications for tumor malignancy." (PMID 38612567, 2024). "Some of these genes were upregulated in our analyses of skin KS (BTAF, VMP1, DCHS1, VCAM1, PLXND1)." (PMID 37740179, 2023). "Given the important role of VMP1 in the autophagy pathway, in pancreatic pathophysiology, and in tumor-resistance mechanisms, VMP1 should be tightly regulated not only at the transcriptional level, but also at the post-translational one." (PMID 37629161, 2023). "The mature miRNA products miR‐21‐5p and miR‐21‐3p were both significantly upregulated in tumours with 3′ VMP1 fusions compared with tumours without host gene fusions (P = 2.2e − 7 and P = 1.2e − 22, edgeR exact test)." (PMID 35182081, 2022). "Recently, it was found that miR-21 indirectly represses the expression of VMP1 through the inhibition of miR-21’s known tumor suppressing target, PTEN, creating a negative feedback loop on VMP1 with increasing miR-21 levels." (PMID 35216281, 2022). "Our results revealed that the expression of VMP1 presented the highest level in GBM, and shared a gradual decrease from the WHO grade III to WHO grade II, indicating that VMP1 might facilitate tumor progression." (PMID 34311746, 2021).
tumor (continued). "The mechanisms by which VMP1 modulates autophagy in mammalian cells have gradually been revealed; however, the functions of VMP1 in tumorigenesis and tumor development as well as its prognostic value are not clearly established." (PMID 34311746, 2021). "Whether the tumor‐promoting effect of VMP1 is related to autophagy induction or is independent of autophagy is also not clear." (PMID 41589276, 2026). "After 2 weeks, VMP1‐OE + BEV treatment profoundly suppressed tumor growth compared to the vehicle control and prolonged the overall survival of mice, suggesting that BEV could abrogate the VEGFA‐dependent oncogenic effect in VMP1‐driven tumors." (PMID 41589276, 2026). "Notably, the impact of gene fusion on tumor malignancy appears independent of VMP1 protein expression." (PMID 38612567, 2024). "We then examined whether and how VMP1 mediates interactions between tumor cells and endothelial cells using an indirect co‐culture system, where human primary endothelial cells (HUVEC) were incubated with conditioned medium (CM) collected from VMP1‐OE GBM cells." (PMID 41589276, 2026). "Therefore, taking into account our previous work reporting that VMP1-mediated autophagy is involved in chemotherapy resistance, it is possible that the VMP1 and CRL4 molecular pathways might be cross-talking during tumor progression." (PMID 37629161, 2023). "Their findings revealed a significant downregulation of VMP1 in human HCC tissues, and this downregulation is closely correlated with multiple tumor nodes, the absence of capsular formation, vein invasion, and poor prognosis of HCC." (PMID 38612567, 2024). "Also, we performed tumor microarrays to determine whether the VMP1 mRNA levels reflected the protein levels, but correlation of mRNA and protein expression could not be assessed due to background staining with the anti-VMP1 antibody." (PMID 31442252, 2019).